NES (nestin)
Diseases named in the same sentence as NES in open-access papers (continued):
Sharing a sentence is not in itself a finding about the gene and the disease.
retinal degeneration (2 papers, 2019 to 2023). Degeneration of the retina. "Müller cells express nestin after acute injury, such as laser photocoagulation or pharmaceutically induced retinal degeneration." (PMID 37298126, 2023). "As gliosis involves macroglia, we investigated their gliotic response to determine the role of S100β and intermediate filaments (IFs) GFAP, vimentin, and nestin during tissue repair in a laser-induced model of retinal degeneration." (PMID 37298126, 2023). "In order to investigate if the data from the mouse model correspond to the characteristics of retinal degeneration in patients, three human retina samples containing drusen and three samples without drusen were stained with the selected gliotic markers (vimentin, nestin, GFAP, and S100β)." (PMID 37298126, 2023). "An upregulation of Nestin expression in the retinal microglia, macrophages, and MG cells has been shown before in adult mice undergoing pharmaceutical induction of retinal degeneration, implicating that Nestin may be used as an early-stage marker of acute retinal injury." (PMID 31185026, 2019).
retinoblastoma (2 papers, 2008 to 2015). A malignant tumor that originates in the nuclear layer of the retina. "Breedable Rb-knockout models of retinoblastoma were independently generated using Cre transgenics with expression driven by Nestin, Chx10 and Pax-6 promoter in progenitor and other cells." (PMID 18489754, 2008). "More recently, stem cell markers have been found expressed in human retinoblastoma cell lines, such as Oct3/4 and Nestin." (PMID 18489754, 2008). "However, the persistence of immature cells in the postnatal Brg1-deficient mouse retina, as seen in electron micrographs and in the expression of progenitor and G2/M genes such as nestin, could indicate conditions that have the opposite effect, i.e. of promoting retinoblastoma." (PMID 26628093, 2015).
schwannoma (2 papers, 2019 to 2023). A benign, usually encapsulated slow growing tumor composed of Schwann cells. "Nestin expression has also been found in Schwannoma and neurofibroma." (PMID 36831419, 2023). "Similarly, the role of PKCθ and nestin in the diagnosis of GISTs is limited because of their lower specificity in other spindle cell tumors, such as schwannomas and smooth muscle tumors." (PMID 31100836, 2019).
Seizure (2 papers, 2018 to 2021). A seizure is an intermittent abnormality of nervous system physiology characterized by a transient occurrence of signs and/or symptoms due to abnormal excessive or synchronous neuronal activity in the brain. "In contrast, nestin and musashi-1 expression were associated inversely with epileptic seizures." (PMID 30297697, 2018). "Given that the role of newborn neurons in the development of chronic epilepsy and related cognitive deficits remains somewhat vague, a study used Nestin-δ-HSV-thymidine kinase-EGFP (Nestin-TK) transgenic mice to ablate adult newborn neurons prior to the onset of acute epileptic seizures in mice." (PMID 34539776, 2021).
Sepsis (2 papers, 2020). Sepsis is defined as life-threatening organ dysfunction caused by a dysregulated host response to infection. "In our study, we used nestin-GFP transgenic mice to assess the effect of sepsis on MSCs in niche." (PMID 35006437, 2020). "In addition, sepsis downregulated the expression of neuronal markers for stem cells (nestin and BLBP), proliferation (Ki67), and differentiation (DCX)." (PMID 33100215, 2020). "To illustrate the effects of sepsis on BM perivascular stromal cells enriched in MSCs (MSC) activity, we used mice expressing GFP under the direction of nestin promoter (Nestin-GFP)." (PMID 35006437, 2020).
skin cancer (2 papers, 2010 to 2019). "We detected that CRABP1, Nestin, and Ephrin B2 are expressed in the intratumoural stroma as well as the tumour invasive front of skin tumours of appendages and BCCs." (PMID 31065284, 2019).
status epilepticus (2 papers, 2015 to 2018). Status epilepticus is defined as a continuous seizure lasting more than 30 min, or two or more seizures without full recovery of consciousness between any of them. "There is evidence that acute seizures can increase nestin expression (Jansson, Wennstrom, Johanson, & Tingstrom, 2009) and following status epilepticus, nestin+ radial glial fibers have been reported." (PMID 28925561, 2018).
stomach cancer (2 papers, 2018 to 2019). "NES, CD34 nor PECAM1 expression was associated with prognosis in urothelial cancer, lung cancer, stomach cancer or glioma." (PMID 30279450, 2018).
ZIKV infection (2 papers, 2019 to 2022). "In order to determine if ZIKV infection targeted NPCs or reduced cortical neurons we performed IF for NeuN (neurons, differentiating neurons) and Nestin (NPCs)." (PMID 30657788, 2019).
acute lymphoblastic leukemia (1 paper, 2016). Leukemia with an acute onset, characterized by the presence of lymphoblasts in the bone marrow and the peripheral blood. "In the BM from mouse models of acute lymphoblastic leukemia (ALL), we have previously determined a protective niche, which is dynamically transient between Nestin+ and α-SMA+ cells,causing the production of reticular fibers in response to chemotherapy." (PMID 27643489, 2016).
adenoid basal cell carcinoma (1 paper, 2019). "Nestin-positive cells were located at the invasive margin (IM) of the tumour of an adenoid basal cell carcinoma." (PMID 31065284, 2019).
AIDS (1 paper, 2021). A syndrome resulting from the acquired deficiency of cellular immunity caused by the human immunodeficiency virus (HIV). "(i) An immuno-histochemistry analysis showed that AIDS-KS spindle cells express Neuroectodermal stem cell marker (Nestin) and oral MSC marker CD29, suggesting an oral/craniofacial MSC lineage of AIDS-associated KS." (PMID 34936683, 2021).
Alazami syndrome (1 paper, 2024). "Building upon these findings, we use Emx1-Cre and nestin-Cre to knock out Larp7, a gene linked to a human NDD called Alazami syndrome (OMIM, # 615071)." (PMID 39479517, 2024). "Furthermore, we use Emx1-Cre and nestin-Cre to knock out Larp7, a gene linked to a human NDD called Alazami syndrome." (PMID 39479517, 2024).
ampullary cancer (1 paper, 2015). "In this study, nestin was a predictor of distant metastasis and poor prognosis in the ampullary cancer patients with mild to strong nestin expression." (PMID 25371063, 2015). "Lacking adequate neovascularization, hypoxia may develop during growth of a primary tumor in early ampullary cancer; thus, nestin/CDK5 temporarily suppresses RAC1." (PMID 25371063, 2015). "The Notch pathway is located upstream of nestin and the NOTCH2 and NOTCH3 genes were overexpressed in ampullary cancer." (PMID 25371063, 2015).
anaplastic thyroid carcinoma (1 paper, 2021). "In another immunohistochemical study, carried out in anaplastic thyroid carcinoma, nestin appeared the most specific marker for stemness." (PMID 34219203, 2021).
aneurysm (1 paper, 2017). Bulging or ballooning in an area of an artery secondary to arterial wall weakening. "In addition, cerebral samples from SAH patients with aneurysm demonstrated the existence of many NSC markers, such as Nestin, vimentin, SOX-2, Musashi-1, and Musashi-2, which possibly contribute to the neural regeneration and functional recovery after aneurysm rupture." (PMID 28133486, 2017).
angiomyolipoma (1 paper, 2017). A neoplasm with perivascular epithelioid cell differentiation often associated with tuberous sclerosis. "Instead, rapamycin shifted the quiescent angiomyolipoma NSC-like cells (nestin+Ki67−) from Galert (nestin+Ki67−pS6+) to G0 (nestin+Ki67-pS6−), consistent with the role of mTORC1 in 'alerting' quiescent stem cells." (PMID 29184052, 2017). "We employed a nestin or GFAP-Cre driver to remove the floxed Tsc1 allele from the NSCs and early and late neuronal progenitors, respectively, since both promoters are active in LAM and angiomyolipoma." (PMID 29184052, 2017).
aortic stenosis (1 paper, 2022). Aortic valve stenosis is a aortic valve disease caused by the incomplete opening of the aortic valve. "Nonetheless, nestin downregulation represents a novel cellular phenotype distinguishing the ascending aorta of normotensive and hypertensive BAV patients diagnosed with aortic stenosis, regardless the sex." (PMID 35439345, 2022).
aortic valve calcification (1 paper, 2016). "Mcp1 deletion in nestin+ cells—but not in endothelial cells only— increases circulating inflammatory cells, but decreases their aortic infiltration, delaying atheroma plaque formation and aortic valve calcification." (PMID 27586429, 2016). "Mcp1 deletion in nestin+ cells—but not in endothelial cells—increased BM egress of inflammatory cells, but reduced inflammatory infiltration in the aorta and significantly delayed atheroma plaque formation and aortic valve calcification." (PMID 27586429, 2016). "Mcp1 deletion in nestin+ cells—but not in endothelial cells only—increased circulating pro-inflammatory monocytes and neutrophils, but decreased their aortic infiltration (without affecting leukocyte adhesion to endothelium), delayed atheroma plaque formation and aortic valve calcification." (PMID 27586429, 2016).
Arrhythmia (1 paper, 2021). Any cardiac rhythm other than the normal sinus rhythm. "Moreover, studies have illustrated that applying MSCs with several factors and substances, for instance, Nestin, Asprosin, IGF-1, and the presentation of cell apoptosis, post-MI arrhythmia." (PMID 34568321, 2021).
asthma (1 paper, 2018). "Consistently, by either intravenous injection of GFP+ MSCs (sorted from bone marrow of Nestin-GFP mice) to the CRE-treated mice, or directly immunizing Nestin-GFP mice with CRE, we observed significantly increased accumulation of GFP+ MSCs in the asthma airways." (PMID 29423331, 2018).
Atopic Dermatitis (1 paper, 2023). "The enrichment analysis of RNAseq automatic Gene Expression Omnibus (GEO) signatures revealed that active compounds of S. polyrhiza (730 target genes) were associated with mouse down gene set including Atopic Dermatitis Nestin-Cre IKK2 (GSE109936)." (PMID 37686078, 2023).
carcinoids (1 paper, 2019). "To the best of our knowledge, we firstly isolated CSCs of a typical carcinoid, which were positive for the prominent CSC markers CD44, CD133 and nestin, confirming their stem cell properties." (PMID 31804333, 2019).
cardiac arrest (1 paper, 2013). Cessation of breathing and/or cardiac function. "In addition, under the acute hypertensive and cardiac arrest conditions, the mRNA levels of PCX and nestin were significantly decreased." (PMID 23502465, 2013). "Under the acute hypertensive and cardiac arrest conditions, PCX and nestin staining was not clear, with a disarranged distribution, but the colocalization of PCX and nestin was apparent under this condition." (PMID 23502465, 2013).
cavernous haemangiomas (1 paper, 2025). "In contrast, we clearly demonstrated a homogeneous nestin expression in the complete endothelium of both capillary and cavernous haemangiomas." (PMID 40149541, 2025). "Other studies reported nestin expression only in capillary but not in cavernous haemangiomas." (PMID 40149541, 2025).
cerebral astrocytoma (1 paper, 2022). An astrocytoma that arises from the cerebral hemispheres. "GFAPδ and nestin-positive cells in cerebral astrocytomas correlates with tumor invasiveness assessed by preoperative neuroimaging investigations." (PMID 35372061, 2022). "Our previous study confirmed this hypothesis and has demonstrated a statistically significant correlation between the grade of GFAPδ immunostaining and the grade of nestin immunostaining in cerebral astrocytoma." (PMID 35372061, 2022).
cholesteatoma (1 paper, 2018). A pathologic process characterized by the proliferation of keratinizing squamous epithelium resulting in the accumulation of keratin and cells in the middle ear and/or mastoid. "We verified the co-localization of β1-integrin with Nestin in the cholesteatoma tissue, whereas the auditory canal skin exhibited the regular β1-intergrin distribution, found in the epithelial layer reviewed in40." (PMID 29670222, 2018). "In addition, co-localization of S100B and Nestin was observable in cells residing within cholesteatoma tissue and auditory canal skin." (PMID 29670222, 2018).
choroid plexus carcinoma (1 paper, 2018). A malignant neoplasm arising from the choroid plexus. "The tumorigenic consequences of persistent MYC expression of this model emerged later in adult mice as choroid plexus carcinoma and ciliary body medulloepithelioma, exposing the select vulnerability of certain subtypes of epithelial cells in the Nestin lineage to tumorigenesis." (PMID 29745900, 2018).
chronic cervicitis (1 paper, 2012). Chronic inflammation of the cervix. "We found that nestin was slightly to moderately expressed in cervical hyperplasia and squamous metaplasia lesions of chronic cervicitis (data not shown)." (PMID 22580387, 2012).
chronic myeloid leukemia (1 paper, 2021). "In contrast with chronic myeloid leukemia (CML), where there is a reduced number of nestin+ MSCs, there is an enrichment of nestin+ cells in AML bone marrow, and this enrichment is essential for the viability and proliferation of AML cells in vitro and in vivo." (PMID 34831055, 2021).
cleft lip (1 paper, 2021). Congenital defect in the upper lip where the maxillary prominence fails to merge with the merged medial nasal prominences. "It has been reported that expression of nestin in the soft tissues of patients with uni- or bilateral cleft lip may indicate a potential increase of tissue regeneration." (PMID 33805026, 2021).
cleft palate (1 paper, 2015). Cleft palate is a fissure type embryopathy that affects the soft and hard palate to varying degrees. "We did not observe any obvious defects or malformations in the palate of Nestin-Cre; Shox2flox/− mutant pups, suggesting that the absence of milk in Shox2-mutant neonatal stomachs was not due to cleft palate malformations." (PMID 26156498, 2015).
dacryoadenitis (1 paper, 2025). Inflammation and enlargement of the lacrimal gland. "Biopsies from healthy human lacrimal glands (n = 9, 61 ± 14.3 years) and non-specific dacryoadenitis (n = 5; 42.8 ± 19.3 years) were immunostained with progenitor cell markers- Nestin, p63 alpha, CK15, ABCG2, c-kit, and CD90, along with RT-PCR." (PMID 40849005, 2025).
delirium (1 paper, 2022). A disorder characterized by confusion; inattentiveness; disorientation; illusions; hallucinations; agitation; and in some instances autonomic nervous system overactivity. "We did not observe any difference in the marker of stemness (Sox2 or Nestin), when comparing the two groups (delirium vs non-delirium) and the two time points." (PMID 36195636, 2022).
dental caries (1 paper, 2021). The decay of a tooth, in which it becomes softened, discolored, and/or porous. "However, nestin is reactivated and its expression increases in the dentin/pulp complex under pathological conditions caused by the preparation of dental caries." (PMID 34443162, 2021).
diabetic nephropathy (1 paper, 2020). "Our previous study about diabetic nephropathy has shown that nestin transiently increased in glomeruli of diabetic rats accompanied with less proteinuria, but nestin expression decreased and proteinuria was aggravated as the disease progressed." (PMID 32371936, 2020).
dysplasia (1 paper, 2019). A usually neoplastic transformation of the cell, associated with altered architectural tissue patterns. "The leukoplakia group was further sub-divided into leukoplakia without dysplasia, leukoplakia with mild/moderate dysplasia, and leukoplakia with severe dysplasia, and the mean expressions of nestin were 1.3±0.48, 0.9±0.88, and 0.17±0.41, respectively." (PMID 31675305, 2019). "Interestingly, the present study showed cytoplasmic and membranous expression of nestin, gradually decreasing from leukoplakia without dysplasia to leukoplakia with mild/moderate dysplasia, and further decreased in leukoplakia with severe dysplasia." (PMID 31675305, 2019).
Dystonia (1 paper, 2022). An abnormally increased muscular tone that causes fixed abnormal postures. "Because some NDD patients reported in the current study suffer from spasticity and/or dystonia and unsteady gait, we also examined whether Nestin-Slitrk2 mice exhibit deficits in fine motor coordination." (PMID 35840571, 2022).
esophageal carcinoma in situ (1 paper, 2017). "In line with immunohistochemistry results, the Western blotting data also showed significant increases of nestin in esophageal carcinoma in situ, esophageal invasive carcinoma and lymph node metastatic carcinoma." (PMID 29029411, 2017). "The immunohistochemistry data showed that the expression levels of nestin were much higher in esophageal carcinoma in situ, esophageal invasive carcinoma and lymph node metastatic carcinoma as compared to normal squamous epithelium group." (PMID 29029411, 2017). "Compared to normal squamous epithelium tissues, the expression of nestin increased in squamous epithelium atypical hyperplasia, esophageal carcinoma in situ and invasive esophageal carcinoma." (PMID 29029411, 2017).
esophageal leiomyoma (1 paper, 2014). "Sustained expression of nestin in spindle cells or epithelial cells of esophageal leiomyoma has also been reported." (PMID 24966803, 2014).
Ewing sarcoma (1 paper, 2008). A small round cell tumor that lacks morphologic, immunohistochemical, and electron microscopic evidence of neuroectodermal differentiation. "Not very surprisingly, nestin expression was also sporadically showed in Ewing sarcomas/PNETs." (PMID 18925963, 2008).
fragile X syndrome (1 paper, 2005). A genetic syndrome caused by mutations in the FMR1 gene which is responsible for the expression of the fragile X mental retardation 1 protein. "The cultured fragile X cells displayed many of the characteristics of neural progenitor cells, including nestin and CD133 expression, as well as the biochemical hallmarks of fragile X syndrome, including CGG repeat expansion and a lack of FMRP expression." (PMID 15649335, 2005).
gliomatosis (1 paper, 2012). "Strong nestin immunolabeling was also detected in normal-appearing, non-dilated microvessels in highly invasive lesions resembling gliomatosis cerebri in the low-generation, invasive GBM xenografts." (PMID 22539956, 2012).
hamartoma (1 paper, 2023). A benign and excessive tumor-like growth of mature cells and normal tissues which grow in a disorganized pattern. "Finally, hamartomas contained cells that expressed Nestin, which identifies NSCs." (PMID 38107199, 2023). "V-SVZ Tsc2wt/wt and Tsc2mut/mut cells were subsequently cultured from Tsc2wt/wt and Tsc2mut/mutx Nestin-CRE-ERT2 neonatal mice and RNA sequencing performed to identify mechanisms that may be responsible for hamartoma and heterotopic neuron generation." (PMID 38107199, 2023).
hemorrhage (1 paper, 2022). Loss of blood from the vascular compartment to the exterior or into nonvascular body space as a result of rupture or severance of the blood vessels. "Finally, Homer1 protein and selumetinib were injected into in situ hemorrhage sites in the brains of Homer1flox/flox/Nestin-Cre+/− mice to study the efficacy of Homer1 in the treatment of ICH by using a mouse cytokine array to explore the potential mechanism." (PMID 35287697, 2022).
hepatoblastoma (1 paper, 2023). Hepatoblastoma (HB) is a malignant hepatic tumor and is the most common pediatric liver cancer. "We noted that the metastatic hepatoblastoma cell line, HLM_2, had higher levels of mRNA abundance of stemness markers Oct4, Nanog, Nestin, and Sox2 compared to the parent cell line, HuH6, so we sought to explore the effects of PIM kinase inhibition on metastatic hepatoblastoma stemness." (PMID 38203596, 2023).